ALDH1A1 (aldehyde dehydrogenase 1 family member A1)
Diseases named in the same sentence as ALDH1A1 in open-access papers (continued):
Sharing a sentence is not in itself a finding about the gene and the disease.
prostate carcinoma (continued). "Silymarin inhibits the expression of ALDH1A1 in prostate cancer, which in turn inhibits the further activation of RARα and Ets1." (PMID 39055491, 2024). "ALDH1A1 promotes the invasion and metastasis of prostate cancer by activating RARα, which further activates Ets1." (PMID 39055491, 2024). "Studies have shown that ALDH1A1+ prostate cancer cells exhibit high tumorigenicity and can promote the progression of tumors transplanted in mice." (PMID 39796106, 2024). "This study, along with others, highlights the biological significance of ALDH1A1 in prostate cancer, positioning it as a promising therapeutic target to prevent metastasis and overcome treatment resistance." (PMID 39796106, 2024). "Recent research published in 2024 led to the discovery that ALDH1A1 promotes metastasis and treatment resistance in prostate cancer through interactions with RAR-dependent transcription and the androgen receptor (AR)." (PMID 39796106, 2024). "High ALDH1A1 expression correlates with lower overall survival, high Gleason score, and high pathologic stage in patients with primary prostate cancer." (PMID 37686694, 2023). "In prostate cancer, the combination of ALDH1A1 inhibitors with other conventional tumor therapies is believed to be a promising strategy in the development of anticancer therapies." (PMID 38139832, 2023). "Inhibition of the Wnt/β-catenin signaling pathway results in a lower viability of prostate cancer cells, which are characterized by high ALDH1A1 expression." (PMID 37686694, 2023). "By contrast to prostate cancer, various cancer types overexpressed ALDH1A1, including breast, colorectal, oesophagus, liver, lung, ovary, pancreas, and stomach." (PMID 36768694, 2023). "In prostate cancer cells, irradiation induces histone methylation at the promoter of the aldehyde dehydrogenase 1A1 (ALDH1A1) gene." (PMID 36142122, 2022). "This study also demonstrated that ALDH1A1 highly expresses in prostate cancer tissues, including secretory epithelial cells and neuroendocrine cells." (PMID 34572930, 2021). "ALDH1A1 promoted invasion and metastasis of prostate cancer by activating the RARα, which further activates Ets1." (PMID 32984354, 2020). "By analyzing data from PLCO database, the genes ALDH1A1 and ALDH1A3 were discovered related to prostate cancer risk." (PMID 33068330, 2020). "The expression level of ALDH1A1 in prostate cancer was significantly different from that in benign prostate hyperplasia samples." (PMID 33068330, 2020). "Upregulation of ALDH1A1 has been observed in primary prostate cancer tissues and metastatic lesions." (PMID 30558236, 2018). "In general, they reported that the Wnt pathway, a significant pathway in CSCs, directly regulates ALDH1A1 level through β-catenin/TCF-dependent transcription as well as ALDH1A1 and β-catenin co-expression in prostate cancer cells." (PMID 30143678, 2018). "ALDH1A1 and Oct-4 gene expression was analyzed because ALDH1A1 is now being widely studied as a prostate cancer stem cell marker and Oct-4 is an embryonic stem cell marker." (PMID 27785389, 2016). "Nanog was found to be upregulated, which enhanced the expression of typical cancer stem cell markers, such as CD44, CD133, and ALDH1A1 in prostate cancer." (PMID 27829864, 2016). "Although ALDH1A1 and ALDH3A1 are most often associated with cancer stem cells, high ALDH4A1 expression has been reported in prostate cancer cells and primary cultures of human prostate cancer." (PMID 39598797, 2024). "In addition, the WGCNA method was used to identify core genes, and when combined with DNBs, four genes including SCD, NARS2, ALDH1A1, and NFXL1 were found to be associated with androgen-related signaling pathways in prostate cancer cells." (PMID 39335669, 2024).
prostate carcinoma (continued). "Our study found that DNBs and four genes (SCD, NARS2, ALDH1A1, and NFXL1), as relevant factors associated with androgen-related signaling pathways in prostate cancer cells, can be further used as indicators of PCa progression after androgen deprivation therapy." (PMID 39335669, 2024). "Therefore, although ALDH enzymes generally aid in detoxifying carcinogens like acetaldehyde, ALDH1A1 paradoxically supports aggressive tumor behavior in prostate cancer." (PMID 39456547, 2024). "Despite AR not being significantly upregulated in the LM, there may still be some regulation of ALDH1A1 by AR as has been previously demonstrated in prostate cancer." (PMID 38361046, 2024). "ALDH1A isoform members have generated considerable interest, as ALDH1A1 has frequently been shown to be expressed in prostate cancer stem cell populations and may contribute to malignancy." (PMID 39335669, 2024). "Also, 24 h incubation of WZ2 with the prostate cancer line (Du145) increased ALDH1A1 levels in cells compared to the control group (p < 0.05)." (PMID 38139832, 2023). "The Wnt pathway was reported to directly regulate ALDH1A1 expression through β-catenin/TCF-dependent transcription, and inhibition of the Wnt/β-catenin signalling pathway was demonstrated to suppress the viability of prostate cancer cells with relatively high ALDH1A1 expression." (PMID 36651035, 2023). "In addition, a series of molecules, including CD44, CD133, integrin α2β1, ALDH1A1, and Bmi1, involved in the regulation of cancer stem cell self-renewal, metastasis, and drug resistance, have also been confirmed in prostate cancer." (PMID 35965510, 2022). "Collectively, these results indicated that Silybin could inhibit prostate cancer by downregulating the expressions of ALDH1A1, RARα and Ets1 in vitro." (PMID 32984354, 2020). "Our results indicated that Silybin showed inhibition of prostate cancer and the mechanism was involving with downregulating ALDH1A1 expression, thereby inhibiting the activation of RARα and preventing the activation of Ets1 to inhibit the growth and invasion of prostate cancer." (PMID 32984354, 2020). "A clinical research indicated that the positive expression of ALDH1A1 in 163 cases of prostate cancer tissue was significantly increased in secretory carcinoma epithelioid cells and neuroendocrine tumor cells and the cells with positive expression had strong clonality and tumorigenicity." (PMID 32984354, 2020). "In conclusion, our study demonstrated that the genetic variants in ALDH1A1 and ALDH1A3 may play an important role in the tumorigenesis of prostate cancer." (PMID 33068330, 2020). "However, rs1330286 in ALDH1A1 and rs4646653 in ALDH1A3 were the only two SNPs that are associated with risk of prostate cancer after FDR regulation (PFDR =0.036 and PFDR =0.036, respectively)." (PMID 33068330, 2020). "The enzyme ALDH1A1 has also been considered a cancer stem marker in prostate cancer." (PMID 32531951, 2020). "Interestingly, the NOTCH signaling indirectly activates the enzymatic activity of ALDH1A1, a well-known marker of prostate cancer stem cells, which are thought to be responsible for tumor recurrence, metastasis and cancer related death." (PMID 29259971, 2017). "Interestingly, NOTCH activates ALDH1A1, an established marker for highly tumorigenic prostate cancer stem cell-like cells." (PMID 29259971, 2017). "Noteably, DU145 xenografts from galiellalactone treated mice showed reduced gene expression of ALDH1A1 compared to untreated DU145 xenografts indicating that galiellalactone may target prostate cancer stem cell-like cells also in vivo." (PMID 21779382, 2011). "Additionally, the study revealed that ALDH1A1 overexpression is associated with high expression of Polo-like kinase 3 (PLK3) in prostate cancer bone metastases, suggesting that ALDH1A1 regulates PLK3 through its interplay with AR and RAR-dependent transcription." (PMID 39796106, 2024).
prostate carcinoma (continued). "Recent studies have revealed that aldehyde dehydrogenase1A1 (ALDH1A1), an aldehyde oxidase that can degrade toxic aldehydes in cells to maintain a stable environment in the cell, was a marker for malignant prostate stem cells and predictor of prostate cancer patients’ outcome." (PMID 32984354, 2020). "In prostate cancer, knockdown of both ALDH1A1 and ALDH1A3 enhanced radio sensitization, but only ALDH1A1 knockdown impaired DNA repair, suggesting a unique role for ALDH1A1 in maintaining cellular homeostasis upon radiation." (PMID 40076923, 2025). "These experiments suggest ALDH1A1 and ALDH1A3 as regulators of a transcriptional program driving CSC phenotype and radioresistance in prostate cancer cells." (PMID 38169509, 2024). "High ALDH1A1 and SCD expression were significantly correlated with prostate cancer’s transition from the hormone-sensitive to castration-resistant state." (PMID 39335669, 2024). "ALDH1A1 and ALDH1A3 influence the phenotype of prostate cancer CSC, which are responsible for metastasis." (PMID 38928275, 2024). "ALDH1A1 and ALDH1A3 are differentially expressed in metastatic tumors of patients with prostate cancer, and their expression levels oppositely correlate with clinical outcomes." (PMID 38169509, 2024). "ALDH1A1-based regulation of PLK3 enhances cellular proliferation and migration, driving tumor progression and metastasis in prostate cancer." (PMID 39796106, 2024). "Our study characterized a differential role of ALDH1A1 and ALDH1A3 genes as regulators of prostate cancer progression and metastatic growth." (PMID 38169509, 2024). "In the case of the prostate cancer cell line DU145, a decrease in ALDH1A1 levels was observed in the cells after 48 h of their incubation with WZ2–WZ4." (PMID 38139832, 2023). "Irradiation triggered methylation of histone H3 on the promoter of aldehyde dehydrogenase 1A1 (ALDH1A1), a CSC marker in prostate cancer cell line, thus stimulating its gene transcription." (PMID 35628460, 2022). "The siRNA-mediated knockdown of ALDH1A1 and ALDH1A3 expressions resulted in radiation therapy sensitization of prostate cancer cells." (PMID 34572930, 2021). "ALDH1A1 and ALDH1A3 were recognized as the main contributors to ALDEFLUOR enzymatic activity in prostate cancer cells." (PMID 34572930, 2021). "ALDH1 has 3 isoforms (ALDH1A1, ALDH1A2 and ALD1A3) and is a marker of both stem cells and CSCs, with expression observed in colon, pancreas, breast and prostate cancers." (PMID 33628765, 2021). "Although prostate cancer has high ALDH2 expression with high OS, its ALDH1A1 expression is indeed very low." (PMID 29552329, 2018). "Growing evidence indicates that ALDH1A1 is a putative CSC marker of several types of solid tumor, including prostate cancer." (PMID 30558236, 2018). "ONC201 significantly downregulated CSC-related genes ABCB5, ALDH1A1, ALDH7A1, WNT16, CD133 and NANOG in DU145 prostate cancer cells." (PMID 28767654, 2017). "ALDH1A1 is known to be regulated by NOTCH signaling and NOTCH1 plays a prominent role in prostate cancer cell proliferation and migration." (PMID 29259971, 2017). "To assess this possibility, we collected whole cell lysates from DU145 and PPC1 cells expressing NT or Arl8b shRNA and probed for prostate cancer stem cell markers, CD44 and ALDH1A1, by immunoblot." (PMID 27105540, 2016). "The results demonstrated that ALDH1A1 and PLK3 may serve as biomarkers to predict metastasis and the development of radio-resistance in prostate cancer patients and may represent potential therapeutic targets to eliminate metastatic cells." (PMID 38928275, 2024). "Nevertheless, another study supports that ALDH7A1 and not ALDH1A1 was the primary enzyme isoform determining the high ALDH activity found in prostate cancer cells." (PMID 37686694, 2023).
prostate carcinoma (continued). "Analog 14 showed the highest antiproliferative activity in the prostate cancer cell lines DU145 and PC3, with IC50 values of 61 and 47 μM, respectively, and analog 14 also showed very low activity as a substrate for ALDH1A1 and ALDH3A1 isoforms, demonstrating the advantage of its higher selectivity." (PMID 36651035, 2023). "To evaluate whether the neuroendocrine phenotype was linked to the induction of stemness properties and plasticity in prostate cancer, we determined the expression of the well-known stem markers CD133 and ALDH1A1." (PMID 32531951, 2020). "Notably, the significant positive correlations between CCL5 and PCSCs-related proteins including ALDH1A1 (p = 0.0001) and STAT3 (p = 0.0001) were observed in the samples of human prostate cancer tissue microarray." (PMID 32300100, 2020). "Although the majority of these studies have focussed on ALDH1A1, ALDH3A1 has been reported to be upregulated in prostate cancer stem cells and in metastatic lesions compared with primary tumours as well as being required for stem cell maintenance and resistance to cytotoxic drugs." (PMID 30642388, 2019). "Results from the current study demonstrated that ABCG2, ALDH1A1, and Oct-4 genes are expressed heterogeneously in single cells isolated from the CWR-R1 prostate cancer cell line, a difference in gene expression would be hard to detect when analyzing bulk cells." (PMID 27785389, 2016). "For prostate cancer, and as above, this could reflect a reduced/lack of activity of ALDH1A1 and ALDH1A2, which oxidise all-trans-retinaldehyde to ATRA." (PMID 36768694, 2023). "Analysis of the expression of ABCG2, ALDH1A1, and Oct-4 genes in single side- and non-side population cells isolated from the CWR-R1 prostate cancer cell line was performed." (PMID 27785389, 2016). "Finally, results demonstrate that the cells isolated based on the side- and non-side population phenotype from CWR-R1 prostate cancer cells have a heterogeneous expression of ABCG2, Oct-4, and ALDH1A1." (PMID 27785389, 2016).
breast tumor (55 papers, 2009 to 2025). "Analyses of Hippo pathway markers in patient samples revealed that compared to their respective normal tissues, enhanced expressions of YAP/TAZ and the stemness markers, SOX2 and ALDH1A1, were observed in both naïve and chemotherapy-treated breast tumors." (PMID 39979255, 2025). "Remarkably, lncROPM was positively correlated with Sox2, Oct4, and ALDH1A1 expression in breast tumor tissues." (PMID 34715882, 2021). "We identify a novel role of ALDH1A1 in some breast tumor cells lines, which, through RAR-dependent VEGF expression regulates tumor angiogenesis." (PMID 30541574, 2018). "In breast tumors, ALDH1A1 expression primes a permissive microenvironment by promoting tumor angiogenesis via retinoic acid dependent mechanism." (PMID 30541574, 2018). "In vivo, when subcutaneously implanted in immunodeficient mice, ALDH1A1 overexpressing breast tumor cells displayed a higher expression of VEGF and MVD." (PMID 30541574, 2018). "Current research has demonstrate that ALDH1A1 enzymatic activity facilitates breast tumor growth." (PMID 40708788, 2025). "Thus, shorter disease‐free survival (DFS), recurrence‐free survival (RFS), and/or OS are reported for patients with high levels of ALDH1A1 in breast tumors." (PMID 36694633, 2023). "In addition, the expression of ALDH1A1, the most widely used cell surface marker for isolating breast tumor-initiating cells, known as cancer stem cells, was also higher in MCF7 and BT-474 cells with over-expressed SPDEF compared to control group." (PMID 37633945, 2023). "Earlier studies have reported increased ALDH1A1 expression in 30% of breast tumor specimens and 34% of inflammatory breast carcinomas, while a recent report showed the presence of epithelial ALDH1 and expanded stromal ALDH1-positive cells in 43% and 69% of breast tumor biopsies, respectively." (PMID 23767668, 2013). "In situ immunostaining of ALDH1A1 has been measured in formalin-fixed, paraffin-embedded breast tumors and it identified both normal and malignant human mammary stem cells; 30% of the breast tumors analyzed presented a relatively small ALDH1-positive cell population." (PMID 19555472, 2009). "Given that increased stem cell biomarker expression was observed in high NOS2 expressing ER- breast tumors, we measured CSC biomarker expressions (ALDH1A1, OCT4, CXCR4, CD133, CD117, CD44 and NANOG) in the control and DETANO treated MCF10A cells." (PMID 36830680, 2023). "Due to the crucial role of VEGF in breast tumor angiogenesis, we examined the expression and release of the growth factor in MCF-7 in which ALDH1A1 activity was impaired." (PMID 30541574, 2018). "Our results, collectively, suggest a close relationship between ALDH1A1 expression levels and the aggressive traits manifested in MCF-7 breast tumor cells, which appears to be predominantly driven by enhanced angiogenesis." (PMID 30541574, 2018). "Furthermore, treatment of hinokitiol in vivo suppressed the growth of xenograft human breast tumors as well as the expression of BMI1 and ALDH1A1 in xenograft tumors." (PMID 29100291, 2017).